NOTCH1 (notch receptor 1)
Diseases named in the same sentence as NOTCH1 in open-access papers (continued):
Sharing a sentence is not in itself a finding about the gene and the disease.
lung cancer (138 papers, 2009 to 2026). A malignant neoplasm involving the lung. "One circulating tumor cell NGS assay in early-stage lung cancer patients showed that more than 50% of lung cancer patients presented four common mutations, including Notch1, EGFR, IGF2, and PTCH1." (PMID 36874015, 2023). "Upregulation of Notch1/3 signaling has been linked to the initiation and progression of lung cancer." (PMID 35258176, 2022). "Our findings, taken together, highlighted the role of Notch1 in determining the maintenance or loss of epithelial phenotype in lung cancer cells exposed to EGFR TKIs." (PMID 33922104, 2021). "In lung cancer, Notch1 co-expression is distinctly enriched for pathways associated with angiogenesis and vascular development, immune system, and Rho GTPase activity." (PMID 34482375, 2021). "Previous studies have broadly shown that perturbation of the NOTCH1 signalling pathway is linked to the pathogenesis of important lung diseases, in particular, lung cancer and lung lesions." (PMID 31605148, 2020). "Among the Notch families, Notch1 has recently been linked to the pathogenesis of EMT in lung cancer." (PMID 32913469, 2020). "Few data have been provided so far concerning the roles of Notch1 in lung adenocarcinoma harboring mutations in other lung cancer driver genes, such as PIK3CA or EGFR (Epidermal Growth Factor Receptor)." (PMID 27847554, 2016). "Previous study had demonstrated that curcumin-induced down-regulation of Notch-1 is associated with the inhibition of cell growth in lung cancer cells." (PMID 27738325, 2016). "Capaccione and colleagues found that SOX9 participates in Notch-1–induced lung cancer cell motility, cell invasion, and loss of E-cadherin expression." (PMID 26384302, 2015). "The Notch1 signalling pathway has been implicated in stem cell maintenance and its aberrant activation has been shown in several types of cancer including lung cancer." (PMID 23651443, 2013). "Interestingly, it was recently reported that Notch1 mutations correlate with a higher tumor mutation burden (TMB) in non‐small cell lung cancer (NSCLC)." (PMID 41026775, 2025). "Moreover, ZEB1 represses HER3 promoter activity by suppressing NOTCH1 in EGFR-mutated lung cancer cells." (PMID 35042943, 2022). "Finally, 34 lung cancer samples analyzed through direct sequencing indicated smoking significantly increased small nucleotide polymorphisms (SNPs) in Notch 1 and 2 and specific SNPs significantly modulated expression levels of downstream signaling pathway molecules." (PMID 29383147, 2017). "However, completely opposite findings were also reported, suggesting that the role of NOTCH1 in lung cancer is highly context-dependent and may be associated with disease subtypes or specific genetic changes." (PMID 26491213, 2015). "RESULTS: Eight PANoptosis-related genes (DAPK2, CAV1, PDK4, IL3RA, NOTCH1, CHMP4B, IRAK1, and SFN) were identified as being significantly associated with lung cancer." (PMID 41760846, 2026). "In our previous study, we demonstrated that UV-irradiated apoptotic lung cancer cells induce WISP-1 expression in CAFs through activation of the Notch1 signaling pathway." (PMID 41522359, 2026). "As contextual evidence, they demonstrated an inverse correlation between Numb, regulated post-translationally in lung cancer, and NOTCH1 accumulation, supported by the expression analysis of the NOTCH-target gene HES family bHLH transcription factor 1 (HES1)." (PMID 40563292, 2025). "Inhibited cell viability, colony formation, migration, invasion, and promoting apoptosis of lung cancer cells; By adjusting the circle_0000190/miR-130a-3p blocked the growth, metastasis, and Notch-1 signaling pathway." (PMID 41220717, 2025). "The reported studies have proven the crucial role of NOTCH1 in lung cancer and NSCLC, and according to the clinical trials reports, 30% of primary human NSCLCs exhibited Notch signaling activation by either NOTCH1 overexpression or numb downregulation." (PMID 41451346, 2025).
lung cancer (continued). "Circular RNAs (circRNAs) are upregulated in lung cancer tissues, and luteolin suppresses lung cancer progression by targeting the circ_0000190/miR-130a-3p/notch-1 signaling pathway." (PMID 40012626, 2025). "This study has identified a novel riboflavin+NOTCH1+ SRCC population in lung cancer cell line and clinical specimens." (PMID 41453945, 2025). "The circ_0000190 was shown to reverse luteolin-induced suppression of lung cancer progression by activating the NOTCH1 signaling pathway sponging miR-130a-3p." (PMID 40563292, 2025). "For instance, increased glycolysis is correlated with dysregulation in lung cancer, called Notch1 signaling, and Notch1/TAZ axis modulation is crucial for lung aerobic glycolysis." (PMID 38841622, 2024). "In summary, we propose that UV-irradiated apoptotic lung cancer cells trigger Notch1-WISP-1 signaling in CAFs, thereby preventing the migration and invasion of cancer cells and CAFs." (PMID 36241874, 2022). "In the present study, we discovered a novel mechanism by which apoptotic lung cancer cells induce CAF reprogramming to promote a tumor-suppressive environment by activating Notch1 signaling, leading to transcriptional upregulation of WISP-1." (PMID 36241874, 2022). "Enhanced expression of the Notch ligand delta-like protein 1 on the surface of ultraviolet-irradiated apoptotic lung cancer cells triggered Notch1-WISP-1 signaling." (PMID 36241874, 2022). "In lung cancer cell lines A549 and H1299 CK2α has been detected as a positive regulator of Notch1 signaling and inhibition of CK2α down-regulated Notch1 signaling, subsequently reducing a cancer stem-like cell population." (PMID 36009534, 2022). "Collectively, these data indicate that apoptotic lung cancer cells trigger Notch1 signaling for WISP-1 production in CAFs, thereby preventing the migration and invasion of lung cancer cells and CAFs." (PMID 36241874, 2022). "Low-dose IFN-γ enhanced the stemness and metastasis of non–small cell lung cancer via the intercellular adhesion molecule-1 (ICAM1)-PI3K-Akt-Notch1 axis." (PMID 35747815, 2022). "Xie proved that lactate produced by Notch1 signaling inhibits the activity of T cell and NK cell and leads to the immune escape of lung cancer." (PMID 36712687, 2022). "Radioresistance via Notch-1 was reported for malignant gliomas and numb/notch-1 signal pathway inhibition enhanced radiosensitivity in lung cancer, melanoma and pancreatic cancer." (PMID 35619161, 2022). "NOTCH1 siRNA can effectively inhibit the expression of NOTCH1 gene, inhibit the proliferation of lung cancer A549 cell lines and increase the sensitivity to chemotherapeutic drugs." (PMID 33909629, 2021). "The results indicate that glycolysis mediated by Notch1/TAZ axis is critical for lung cancer growth." (PMID 34482375, 2021). "Previous studies revealed that miR-146a-5p promotes lung cancer cell proliferation by targeting claudin-12, and overexpression of miR-146 or knockout of its target gene, notch 1, inhibits mouse neural stem cell proliferation in serum-free medium." (PMID 33531066, 2021). "Here, we provided evidence to support a link between Notch1 signaling induced lactate and lung cancer immune escape through inhibition of cytotoxic T cell and NK cell activity." (PMID 34482375, 2021). "The synergistic reduction of NRF2 and NOTCH1 signaling pathways promotes ROS accumulation and IR-induced apoptosis, suggesting a possible future strategy to overcome radioresistance in lung cancer patients." (PMID 34141616, 2021). "Our findings on lung cancer in mice upon Kras activation combined with Notch1 inactivation clearly show an accumulation of tumor cells in the lumen of bronchioles protruding from the bronchiolar epithelium." (PMID 34257546, 2021). "Our study provides a genetically engineered mouse model to investigate tumorigenesis of autochthonous KrasLSL-G12V driven lung cancer upon conditional Notch1 knock-out." (PMID 34257546, 2021).
lung cancer (continued). "Notch1 is involved in the innate immune system and Notch1 knockdown in lung cancer enhances innate immune recruitment." (PMID 34482375, 2021). "In our study, we aimed to investigate the effects of conditional Notch1 deficiency on carcinogenesis and TAZ expression using an autochthonous KrasLSL-G12V driven lung cancer mouse model." (PMID 34257546, 2021). "Herein, we demonstrate in lung cancer that Notch1 promotes glycolytic gene expression through functional interaction with histone acetyltransferases p300 and pCAF." (PMID 34482375, 2021). "Based on analysis of the COSMIC database, NOTCH1 and ARID1A are reported to be associated with lung cancer." (PMID 34136379, 2021). "Therefore, we show here for the first time in an in vivo model that Notch1 deficiency is able to induce tumor cell accumulation even in central airways in a mutated Kras driven lung cancer mouse model, which may represent the early steps of a typical multistep carcinogenesis." (PMID 34257546, 2021). "Lung cancer patients who had increased glucose uptake assessed by 18FFDG PET scans showed increased Notch1 expression and increased TAZ expression." (PMID 34482375, 2021). "In lung cancer, co-expression of NOTCH-1 and vascular endothelial growth factor-A predicts poor survival." (PMID 32655137, 2020). "It has been reported that TRIB3 regulated Notch1 activation in lung cancer cells and Notch1 activation is known to lead to radioresistance of TNBCs." (PMID 30678233, 2019). "NOTCH1 expression has been proposed as a poor prognostic factor for many types of cancer, such as breast, gastric and lung cancer." (PMID 29721172, 2018). "Notch1 signaling is involved in the upregulation of Survivin expression in lung cancer cells as well, which is synergized by HIF-1α." (PMID 28030818, 2017). "It has been reported that Notch1 plays a key role in lung cancer cell migration and invasion, which are both key cellular attributes necessary for metastasis." (PMID 28402268, 2017). "The Notch 1 protein has also been known to suppress tumor proliferation under normoxia in lung cancer; however, it exhibited the opposing role of tumor promotion under hypoxia conditions." (PMID 28422717, 2017). "For example, curcumin inhibits the transcription of the ezh2 gene; curcumin degrades EZH2 mRNA through elevated levels of miR-101 and miR-let 7c; and the decreased level of EZH2 resulted in the downregulation of NOTCH1 in lung cancer." (PMID 27049834, 2016). "In the current study, we found that compared with RNAi knockdown of EZH2, knockdown of NOTCH1 mimicked the effects on lung cancer cell proliferation, cell cycle distribution, and cell migration." (PMID 27049834, 2016). "We also showed that CO significantly enhanced cleavage of Notch1, which corresponded to decreased Notch1 expression in the stroma surrounding lung cancers in Kras mice treated with CO." (PMID 26993595, 2016). "Further, our studies show that NOTCH1 depletion or treatment with γ-secretase inhibitors reverse resistance in multiple gefitinib-resistant lung cancer cells, suggesting a strong translational potential of our above mechanistic findings." (PMID 27456471, 2016). "We also expressed miR-200c or NOTCH1 siRNA in multiple lung cancer cells with different oncogenic backgrounds." (PMID 27456471, 2016). "To evaluate the expression of HO-1 in primary tumors, we employed human lung carcinoma specimens from 30 patients and performed immunohistochemical analysis of HO-1, Notch1 and P-Erk1/2 in these samples." (PMID 26993595, 2016). "Activation of Notch-1 signaling was demonstrated in gefitinib-resistant lung cancer cells undergoing EMT." (PMID 25990317, 2015). "Correlative studies based on immunohistochemical (IHC) staining of lung cancer tissues for NOTCH1 expression have led to contradictory conclusions." (PMID 26491213, 2015).
lung cancer (continued). "Consistently, a recent report has shown that the expression of Galectin-1, a glycan binding protein overexpressed in lung cancer, increased the expression of both Jagged2 and NOTCH1 and promoted Lewis lung carcinoma metastasis." (PMID 26491213, 2015). "For instance, during the development of non-small cell lung cancer, Notch2 mediated cell differentiation, whereas Notch1 promoted the initiation and development of lung cancer." (PMID 26563263, 2015). "In lung cancer, previous studies have shown that NOTCH1 acts as a driver of lung tumor initiation, growth, and metastasis." (PMID 26491213, 2015). "The meta-analysis results suggested that Notch1 expression was significantly higher in lung cancer compared with normal tissues, and correlated with lymph node metastasis and TNM stages." (PMID 25996086, 2015). "Herein, we review recent findings about the role of NOTCH1 in lung cancer and discuss its potential usefulness as both a therapeutic target and a biomarker for lung cancer." (PMID 26491213, 2015). "Some researchers demonstrated that the up-regulation of Notch receptors and ligands such as Notch-1 and Jagged-1 will probably predict relatively metastasis in lung cancer." (PMID 24423157, 2013). "In this study, we investigated the possible relationship between CK2α and Notch1 signalling in lung cancer cells." (PMID 23651443, 2013). "In summary, we report that CK2α is a positive regulator in the Notch1 signalling pathway, and that inhibition of CK2α down-regulates Notch1 signalling in human lung cancer cells." (PMID 23651443, 2013). "Here, we show, for the first time, that CK2α is a positive regulator of Notch1 signalling in lung cancer cell lines A549 and H1299." (PMID 23651443, 2013). "The overexpression of Notch1 increases the resistance of lung cancers to cisplatin and paclitaxel, the resistance of breast cancers to melphalan and mitoxantrone and the resistance of cervical cancers to doxorubicin." (PMID 23671619, 2013). "Down-regulation of Notch1 transcriptional activity was demonstrated after the silencing of CK2α in lung cancer cells." (PMID 23651443, 2013). "An active ADAM17 regulates EGF receptor expression through activating NOTCH1 that was demonstrated to affect proliferation and survival of lung cancer cells, and tumorigenicity of non-small cell lung cancer." (PMID 22239941, 2012). "In this regard, our results demonstrated that silencing of SOX2 significantly reduces the protein expression level of oncogenes-WNT1, WNT2, c-MYC and NOTCH1 in human lung cancer and further revealed other target cancer genes of SOX2." (PMID 22615765, 2012). "NOTCH1 was also upregulated in lung cancer samples from uranium miners with high exposure to arsenic." (PMID 23028920, 2012). "In contrast, activation of SIRT1 signaling through the use of the small molecules SRT1720 or SRT2183 inhibited DLL4-mediated induction of HEY1 and HEY2 expression, indicating that SIRT1 negatively modulated DLL4/Notch1 signaling in lung cancer-derived ECs." (PMID 23028940, 2012). "The study revealed that Luteolin suppressed the growth of lung cancer cells, metastasis, and Notch-1 signaling pathway by regulating the circ_0000190/miR-130a-3p axis in vitro and by regulating circ_0000190, Luteolin suppressed the tumor growth of lung cancer in vivo." (PMID 36992138, 2023). "CK2α was shown to be a positive regulator of Notch1 signaling in A549 and H1299 lung cancer cells." (PMID 36766747, 2023). "In lung cancer, increased circ_0003998 and circ_POLA2 regulate cell proliferation and invasion, resulting in a poor survival rate in lung cancer patients relying on miR-326, which suppresses its target genes, Notch1 and GNB1." (PMID 36769372, 2023). "Moreover, the significance of inhibiting Notch1 signaling in preventing lung cancer development has also been clarified and indicated Notch1 as a promising therapeutic target and biomarker of lung cancer." (PMID 36818671, 2022).
lung cancer (continued). "In our future work, whether NLE1 regulates lung cancer through Notch1 signaling and the molecular regulatory mechanism between NLE1 and CDK1 would be further explored and investigated." (PMID 36818671, 2022). "Furthermore, CK2 has been reported as a positive regulator of Notch1 signaling in lung cancer cell lines A549 and H1299." (PMID 36009534, 2022). "In addition, the increased levels of extracellular lactate are closely associated with the Notch1/TAZ axis, which can inhibit the activity of cytotoxic T cells and lead to the proliferation and migration of lung cancer cells." (PMID 36505423, 2022). "On the other hand, some authors have demonstrated that the Notch-1 pathway could suppress cell proliferation and induce apoptosis in human lung carcinoma and esophageal squamous cell carcinoma." (PMID 35982489, 2022). "Notch1 stimulates glycolysis in lung cancer and TAZ promotes this effect via interaction." (PMID 34482375, 2021). "In contrast to Notch1 and Notch3, which are regarded as oncogenic factors responsible for lung cancer development, whether Notch2 has similar roles should be further investigated." (PMID 34485133, 2021). "Our data show that Notch1 regulates Notch1 knockdown lung cancer cells regulates glycolytic gene expression, glucose uptake, and the level of lactate, a metabolite that can facilitate tumor growth, indicating that Notch1 is a key transcription factor for the regulation of aerobic glycolysis." (PMID 34482375, 2021). "Indeed, the alterations found in these genes such as RYR2, NOTCH1 and DMBT1 have strong association with high tumor burden and tumorigenesis, possibly resulting in a worse prognosis in lung cancer patients." (PMID 34336686, 2021). "Interestingly, ST6GAL1 has been shown to regulate Notch1, Hes1, matrix metalloproteinases (MMPs) and vascular endothelial growth factor (VEGF) in lung cancer and altered α2-6 sialylation has been linked to lung cancer progression." (PMID 34290711, 2021). "Indeed, after the exposure of lung cancer cells to radiation, the expression of NOTCH1 is up-regulated, while in cells knocked-down for NRF2, NOTCH1 and its downstream gene HES1 are down-regulated." (PMID 34141616, 2021). "Interestingly, as analyzed from the TCGA lung cancer datasets and KM plot database, high mRNA levels of Notch1 significantly correlate with poor overall survival and disease progression of LUSC patients." (PMID 33976158, 2021). "Targeting Notch1- TAZ axis could enhance the efficacy of immunotherapy through the inhibition of aerobic glycolysis in lung cancer." (PMID 34482375, 2021). "Whether these mutations can be combined with NOTCH1, EGFR and ARID1A mutations as tumor markers in the diagnosis of early lung cancer merits further investigation." (PMID 34136379, 2021). "Because knockdown of TAZ reversed the ability of Notch1 to increase aerobic glycolysis in lung cancer, we next asked whether hippo/TAZ signaling interactions with Notch1 signaling promotes aerobic glycolysis." (PMID 34482375, 2021). "Notably, aerobic glycolysis was critical for Notch1/TAZ axis modulation of lung cancer growth in vitro and in vivo." (PMID 34482375, 2021). "Notch1 signaling, dysregulated in lung cancer, is correlated with increased glycolysis." (PMID 34482375, 2021). "We then examined whether glycolysis plays a role in Notch1/TAZ axis-mediated regulation of lung cancer cell proliferation." (PMID 34482375, 2021). "Thus, we aim to elucidate the effects of conditional Notch1 deficiency on carcinogenesis and TAZ expression in lung cancer." (PMID 34257546, 2021). "In addition, previous studies have shown that NOTCH-1 can regulate EGFR expression in lung cancer cells." (PMID 32655137, 2020).